TMPRSS2 (transmembrane serine protease 2)
Diseases named in the same sentence as TMPRSS2 in open-access papers (continued):
Sharing a sentence is not in itself a finding about the gene and the disease.
COVID-19 (continued). "The TMPRSS2 cell entry of SARS-CoV-2 inhibitors camostat mesylate, nafamostat, and bromhexine may treat COVID-19." (PMID 32806657, 2020). "In summary, we demonstrate that TMPRSS2 and furin are essential for activation and multiplication of the novel emerged SARS-CoV-2 in human airway epithelial cells and provide promising drug targets for treatment of COVID-19." (PMID 32703818, 2020). "Therefore, the inhibition of both TMPRSS2 and cathepsin L display promising treatment approaches for SARS-CoV-2 infection/COVID-19." (PMID 32668803, 2020). "From the pathophysiological point of view, the spike protein in the morphology of COVID-19 bind to angiotensin-converting enzyme (ACE)-receptors on alveolar epithelial cell type 2 (AT2), primed by transmembrane protease serine 2 (TMPRSS2) to allow coronavirus entry." (PMID 33708124, 2020). "Ongoing trials directly and indirectly target COVID-19-related endothelial dysfunctions: i.e., a virus-cell entry using recombinant ACE2 and TMPRSS-2 blockade, immunomodulatory therapies such as anti-IL-6 strategies, complement blockade, and coagulation activation." (PMID 32546188, 2020). "Because TMPRSS2 is androgen regulated, several studies have advocated for the use of antiandrogens and androgen deprivation therapies (ADT) as a potential therapeutic option in COVID-19, suggesting possible protection against SARS-CoV-2 infection." (PMID 32641750, 2020). "The serine protease TMPRSS2 required for SARS- CoV-2 entry into host cells, highly conserved among the MERS-CoV, SARS-CoV-1, and SARS-CoV-2 viruses, has been identified as a promising target for treatment of COVID-19." (PMID 32806657, 2020). "As in SARS-CoV, a TMPRSS2 inhibitor has been shown to block SARS-CoV-2 from cellular entry, and may serve as a treatment for COVID-19." (PMID 32574196, 2020). "TMPRSS2, a cellular serine protease that primes the spike protein of SARS-CoV-2 and has been shown to be important in facilitating viral entry into cells, is down-regulated in the lungs of fatal COVID-19 cases." (PMID 33082228, 2020). "Hoffmann and coworkers found that infection by SARS-CoV-2, the virus responsible for COVID-19, may depend almost exclusively on the host cell factors ACE2 and TMPRSS2." (PMID 32545518, 2020). "TMPRSS2 is a critical protease that enables the entry of SARS-CoV-2 in angiotensin-converting enzyme 2 (ACE2) receptors, explaining why men tend to die more from COVID-19." (PMID 32825068, 2020). "A recent COVID-19 study revealed that SARS-CoV-2 utilizes the same cell entry method used by SAR-CoV, namely, relying on the ACE2 receptor and priming of the spike protein by TMPRSS2." (PMID 33746739, 2020). "Severe acute respiratory syndrome coronavirus 2 (SARS-CoV-2), the virus responsible for COVID-19, employs two key host proteins to gain entry and replicate within cells, angiotensin-converting enzyme 2 (ACE2) and the cell surface transmembrane protease serine 2 (TMPRSS2)." (PMID 33310900, 2020). "ACE2 and TMPRSS2 can be found in several tissues but – interestingly – apparently not in the lung, the organ in which COVID-19 most often manifests as a severe disease." (PMID 32591346, 2020). "While cardiometabolic risk factors can be used to stratify patients in terms of their vulnerability to COVID-19, our data do not provide consistent support that the expression of ACE2 or TMPRSS2 represents causal mechanisms underlying these associations." (PMID 33391794, 2020). "This, in conjunction with the observation from the in silico screen that suggests reduced mRNA expression of TMPRSS2 in cells exposed to selumetinib, identifies the MEK inhibitor as a plausible candidate for further evaluation in experimental models relevant to COVID-19." (PMID 33312454, 2020).
COVID-19 (continued). "Although we detected ACE2, TMPRSS2, CAS-3, and SARS-CoV-2 nucleocapsid protein in the outermost layer of plucked human HFs—suggesting a possible entry route for the virus into follicular epithelial cells—only a subset of COVID-19 patients develop symptoms of telogen effluvium (TE)." (PMID 41298780, 2025). "However, in this case, this quotient did not serve to discriminate between Enceph patients with and without COVID-19, because in Enceph patients with increased TMPRSS2 the 25-kDa fragment was elevated in a higher proportion than that of the 55-kDa species." (PMID 40036349, 2025). "Thus, our findings do not support a relationship between TMPRSS2 expression levels and COVID-19 severity." (PMID 40729397, 2025). "In this study, we monitored the levels of ACE2, TMPRSS2, IL-17A, ADAM-17, VD, and AP in NPS, serum, and saliva to assess their impact on health status, further supporting the need for multi-biomarker approaches in evaluating COVID-19’s effects on the immune system." (PMID 40003732, 2025). "predicted the rare expression of ACE2 and TMPRSS2 in the salivary glands and ducts of healthy volunteers; however, they subsequently found that receptors and SARS-CoV-2 infection were more frequent in the salivary glands and ducts during COVID-19 autopsy using in situ hybridization." (PMID 38975331, 2024). "In this study, we analyzed ACE2 and TMPRSS2 expression in both non-COVID-19 and COVID-19 autopsies." (PMID 38975331, 2024). "Other TMPRSS2 variants such as rs17854725 SNV, showed a significant negative correlation with MIP-1α, while rs429442 SNV showed a significant negative correlation with IL-1Ra and IL-8 in COVID-19 patients." (PMID 38855114, 2024). "Interestingly, they only found frequency differences for the TMPRSS2 rs12329760C>T variant in the group receiving invasive oxygen therapy, but they did not identify an association between CD147 rs8259T>A and COVID-19 susceptibility or severity." (PMID 37630479, 2023). "Notably, since TMPRSS2 is highly expressed in lung cells, this may explain why the exclusive endosomal entry inhibitor hydroxychloroquine (HCQ) failed in treating COVID-19 patients." (PMID 37896901, 2023). "Additionally, the soluble serum concentrations of ACE2 and TMPRSS2 were elevated in severe COVID-19 patients, compared to those with non-severe COVID-19 (P < 0.01 and P < 0.001, respectively)." (PMID 38444707, 2023). "At the same time, we speculate that LUAD patients infected with COVID-19 may not be suitable for TMPRSS2 inhibitors treatment." (PMID 36992839, 2023). "TMPRSS2 is also strongly related with other genes involved in prostate cancer, like ERG, ETV5 and AR, whose characterization could help to clearly classifying COVID-19." (PMID 37287057, 2023). "Similarly, there was a significant negative correlation between the concentration of TMPRSS2 in severe COVID-19 patients and the relative expression of miR-200b-3p (r = -0.4, P = 0.03) and miR-214-3p (r = -0.4, P = 0.04)." (PMID 38444707, 2023). "Exploring the potential mechanisms contributing to the interplay between COVID-19 and PCa suggests an apparent correlation between the targets of SARS-CoV-2 on host epithelial cells and the genetic anomalies and molecular markers of PCa, such as AR and TMPRSS2." (PMID 37371774, 2023). "Moreover, the serum concentration of TMPRSS2 was significantly higher in patients with non-severe COVID-19 (P < 0.01) and severe COVID-19 (P < 0.0001) than in the control group." (PMID 38444707, 2023). "Adults with asymptomatic SARS-CoV-2 infection faced a higher PP of COVID-19-related long-term consequences, which may be related to increased viral entry mediators such as ACE2 and TMPRSS2 in respiratory epithelial cells, and increased pro-inflammatory cytokine production." (PMID 36674367, 2023). "Additionally, ACE2 and TMPRSS2 serum concentrations were higher in severe COVID-19 cases than in non-severe cases." (PMID 38444707, 2023).
COVID-19 (continued). "Besides, the discrepancy of COVID-19 related outcomes between male and female participants could be attributed to the differences in sex hormones, expression levels of ACE2 and Transmembrane protease serine 2 (TMPRSS2), and lifestyles." (PMID 37889436, 2023). "Additionally, the contribution of MUO-related upregulated Transmembrane Serine Protease 2 (TMPRSS2) expression, hyperglycemia, and weakened immune surveillance to the poorer prognosis of COVID-19 in the corresponding patient population are also being in-depth investigated." (PMID 37877121, 2023). "In addition, the recently identified small molecule inhibitor of TMPRSS2, N-0385, inhibited SARS-CoV-2 infection in human lung cells and showed the high efficiency of prophylactic and therapeutic benefits in the transgenic mouse model of severe COVID-19." (PMID 37189326, 2023). "The co-expression of ACE2, TMPRSS2, and NRP1 in the proximal tubules of normal kidney tissue should assist the infection of the virus and it could represent a mechanism for the direct kidney damage reported in patients affected by COVID-19." (PMID 38255667, 2023). "In addition, prolonged hyperglycemia could worsen the course of COVID-19 via glycation of pancreatic ACE2 and the transmembrane serine protease 2 (TMPRSS2), thus facilitating the SARS-CoV-2 binding and entrance to pancreatic β-cells." (PMID 35326383, 2022). "This exploratory study showed that four polymorphisms associated with COVID-19 severity (ACE2 rs2285666, ACE2 rs2074192, TMPRSS2 rs12329760, and TMPRSS2 rs2070788), did not appear to predispose for the development of long-COVID symptoms in previously hospitalized COVID-19 survivors." (PMID 36360172, 2022). "Therefore, the downregulation of ACE2, CD147, FURIN, and TMPRSS2 genes and the upregulation of BMAL1 may offer a therapeutic strategy against COVID-19 and periodontitis." (PMID 36366382, 2022). "Therefore, we examined in the present study whether the small molecules of quercetin, glabridin, gallic acid, and chrysoeriol, regulate ACE2, TMPRSS2, NOX2, and MCP-1 to mediate therapeutic protection against COVID-19." (PMID 36187008, 2022). "Therefore, camostat mesylate, which has a favorable safety profile, might be suitable for prevention and treatment of COVID-19 and related viral diseases, because SARS-CoV, MERS-CoV and several influenza A viruses depend on TMPRSS2 for spread and pathogenesis." (PMID 35412356, 2022). "As such, in this study, we screened TMPRSS2 active site small-molecule inhibitors from the FDA that may inhibit TMPRSS2 activity, thereby blocking SARS-CoV-2 entry into cells and providing a possible therapeutic approach for COVID-19." (PMID 35807455, 2022). "In addition, anti-androgens target TMPRSS2 and reduce SARS-CoV-2 virus entry in lung cells, which may at least in part explain why men with COVID-19 have a worse prognosis when compared to women." (PMID 35529872, 2022). "Furthermore, ACE-2 and TMPRSS2 are highly expressed in proximal tubules, where SARS-CoV-2 particles could be detected postmortem in the respective podocytes from COVID-19 patients, hinting that the novel coronavirus can directly target the kidneys." (PMID 35928822, 2022). "Furthermore, to our knowledge, no study has as yet investigated serum TMPRSS2 levels as a potential biomarker in COVID-19." (PMID 35455738, 2022). "The results of our study of the expression of ACE2 and TMPRSS2 suggest that smoking is unlikely to impact the likelihood of SARS-CoV-2 infection in the upper airways but that it may play a significant role in COVID-19 disease progression and severity." (PMID 36307504, 2022). "The reason is not completely clarified, but there are studies that age-dependent expression of some host proteins, such as angiotensin-converting enzyme 2 (ACE2) and transmembrane serine protease 2 (TMPRSS2), could be responsible for less severe forms of COVID-19 in children." (PMID 35558368, 2022).
COVID-19 (continued). "Nevertheless, comprehensive data regarding ACE2 and TMPRSS2 expression in exocrine cells remain discrepant because researches that discover entry factors outside β-cells do not identify SARS-CoV-2 nucleocapsid protein in COVID-19 pancreas tissues." (PMID 36992767, 2022). "In addition to detected significant changes in expression of ACE2 and TMPRSS2 in AKI and PMV models, we also identified novel candidates that mediate cross-talk between the lung and kidney, which could be pertinent to COVID-19." (PMID 35123426, 2022). "As clinical manifestations in the cases of both COVID-19 and PRAD may metastasize and localize in other organs and systems, we carried out a functional assessment of TMPRSS2 and CXCL10 to identify what additional genes and their protein products are related to COVID-19 and PRAD prognosis." (PMID 36239108, 2022). "Kragstrup and colleagues recently assessed ACE2, but not TMPRSS2, in hospitalized patients with COVID-19, and reported that higher baseline plasma ACE2 levels were significantly associated with poorer overall outcome (defined by worse WHOmax category) at 28 days." (PMID 35455738, 2022). "This may indicate ACE2 and TMPRSS2 transcriptomic changes are related to the consequences of SARS-Cov2 and not to the molecular predisposition to develop severe COVID-19 symptoms." (PMID 34315903, 2021). "Selected hits were evaluated in the TMPRSS2 biochemical assay and the SARS-CoV-2-S pseudotyped particle entry assay, and a number of novel inhibitors were identified, providing a starting point for the further development of therapeutic drug candidates for COVID-19." (PMID 34501332, 2021). "It has recently been reported that high concentrations of bromhexine, an expectorant and inhibitor of TMPRSS2 currently used in clinical trials against COVID-19, unlike another expectorant, ambroxol, may favor the formation of syncytia." (PMID 34201505, 2021). "Unlike the higher levels of ACE2 and/or TMPRSS2 expression in men and those with health comorbidities, the driver for racial and ethnic disparities with COVID-19 appears principally to be socioeconomic inequalities that are exacerbated by the existence of comorbidities." (PMID 33476304, 2021). "In addition, ACE2 and TMPRSS2 enterocyte expressions are not different in COVID-19 compared to non-IBD controls." (PMID 34697723, 2021). "Collectively, we strongly believe that the 11 drugs, except Camostat and Nafamostat, evaluated in this study are promising noncovalent TMPRSS2 inhibitors, and their potency for COVID-19 treatment could be further investigated." (PMID 34209110, 2021). "To see whether there is any potential link between tissue TMPRSS2/ACE2 expression, morbidity and/or fatality of SARS-CoV-2 infection, we set out to analyze the correlation of gene expression with SARS-CoV-2 infection and COVID-19 death." (PMID 34832534, 2021). "Co-expression of ACE-2 and TMPRSS2 could be the GI entry route for SARS-CoV-2 not only in pneumocytes but also in absorptive enterocytes of ileum and colon and may account for the frequent GI symptoms of COVID-19." (PMID 34399734, 2021). "The collective effect of TMPRSS2/HAT and ADAM17 on activation of the S protein on COVID-19 and the ACE-2 receptor on type-2 pneumocytes again might be attributable to the high rate of transmission of COVID-19 from person to person." (PMID 34305892, 2021). "Lower expression or lack of expression of ACE2 and TMPRSS2 could have crucial implications for the design of future therapeutic options for COVID-19." (PMID 33853637, 2021). "We demonstrated that air pollution exposure and IPF upregulate the protein levels of ACE2 and TMPRSS2 both in human tissue samples and animal studies, thereby providing a basis for their roles in spreading SARS-CoV-2 infection and worsening the condition of COVID-19." (PMID 33706759, 2021).
COVID-19 (continued). "Finally, expression analysis from nasopharyngeal swab samples compared to BAL on an independent case-only cohort demonstrates similar expression patterns of ACE2, TMPRSS2 and TMPRSS2/ACE2 on upper and lower respiratory tracts of COVID-19 patients under mechanical ventilation." (PMID 33958627, 2021). "Here, our data support the idea that an agonist of TMPRSS2/ACE2 may improve COVID-19 death incidence in men; however, it may not be proper to administer it in female patients because ACE2 expression is positively associated with female COVID-19 death." (PMID 34832534, 2021). "In terms of ER ligands, on the basis that agonists inhibit TMPRSS2 expression it would be ER agonists rather than, as is the case for AR, antagonists that may be useful in COVID-19." (PMID 34328182, 2021). "Interestingly, ACE2 and TMPRSS2 expression was increased in COVID-19 vs non-COVID-19, with respectively 2.3% and 21% of COVID-19 epithelial cells expressing these genes." (PMID 33473155, 2021). "However, considering the clinical complications of COVID-19 in different organs, there is no strong association between the abundance of ACE2/TMPRSS2 co-expression and clinical features of the disease and the severity of complications." (PMID 34096226, 2021). "In this study, we demonstrated that hesperidin and its aglycone, hesperetin, might provide benefits in fighting COVID-19 via blocking the binding of the S protein of SARS-CoV-2 to the human cellular receptor ACE2 and reducing the protein expression of ACE2 and TMPRSS2." (PMID 34444960, 2021). "In contrast, urinary ACE2 and TMPRSS2 did not correlate with AKI in COVID-19." (PMID 34113632, 2021). "On the one hand, this experiment was limited by the number of database samples and clinical specimens; on the other hand, it was limited by the biological test of ACE2 and TMPRSS2 expression levels from tissue specimens of patients who were not confirmed with COVID-19." (PMID 34412632, 2021). "Therefore, transmembrane protease serine 2 (TMPRSS2), another main co-factor needed by the SARS-CoV-2 to enter human cells, might be an alternative target for COVID-19." (PMID 34445368, 2021). "Moreover, according to the autopsied data, we evidenced an increase of glycosylated ACE2 and TMPRSS2 protein content in DM specimens compared to Non-DM specimens from non-COVID-19 hearts." (PMID 33962629, 2021). "However, in autopsy kidney samples of COVID-19 patients, SARS-CoV-2 nucleoprotein was detected in both ACE2+ and TMPRSS2+ renal tubular cells, whereas the RNAscope® Assay targeting the SARS-CoV-2 Spike gene was positive mainly in the distal tubular cells and seldom in the proximal tubular cells." (PMID 34136484, 2021). "Although the safety of TMPRSS2 inhibition has not been clinically proven yet, drugs with proteolytic inhibition activity towards TMPRSS2 (eg, camostat mesylate and nafamostat mesylate) are currently being pursued for the treatment of COVID-19." (PMID 33969249, 2021). "Therefore, overexpression of TMPRSS2 by androgen may implicate the testosterone in the pathogenesis of SARS-CoV-2 infection and COVID-19 severity." (PMID 34568081, 2021). "Considering the indispensable function of TMPRSS2 in the pathogenicity of SARS-CoV-2, several therapeutics that are effective in attenuating androgen receptor signaling could be repurposed for the treatment of patients with COVID-19." (PMID 34001144, 2021). "The degree to which nonhuman animal polymorphisms for ACE2 and TMPRSS2 resemble those in humans, therefore, is likely to predict indirect and direct transmission of the SARS-CoV-2 virus and subsequent presentation of the disease COVID-19." (PMID 34359172, 2021). "They suggested that although the differences in expression of these markers may not explain COVID-19 severity between genders, therapy targeting the activity of TMPRSS2 could be used as an alternate treatment." (PMID 34574709, 2021).